CRP (C-reactive protein)
Diseases named in the same sentence as CRP in open-access papers (continued):
Sharing a sentence is not in itself a finding about the gene and the disease.
type 2 diabetes (continued). "The aim of this study was to determine the clinical value of serum glycated albumin and high-sensitivity C-reactive protein (hs-CRP) levels for the prediction of CAD using logistic regression model in patients with type 2 diabetes." (PMID 17178005, 2006). "The same may apply to other immunological traits like blood levels of CRP and immune-mediated diseases such as inflammatory bowel disease and type 2 diabetes, which also are considerably less polygenic than MDD." (PMID 41306196, 2025). "The analysis reveals that horizontal pleiotropy drives genetic correlations between MetS and traits such as type 2 diabetes, C-reactive protein (CRP), sleep apnea, and cholelithiasis, while vertical pleiotropy links body mass index (BMI) with MetS and MetS with cardiovascular diseases." (PMID 40956352, 2025). "Additionally, the combination of dapagliflozin and metformin treatment significantly reduced PRAT layers in obese patients with type 2 diabetes, accompanied by reductions in plasma leptin, C-reactive protein, and urinary microalbumin levels." (PMID 40487756, 2025). "Studies involving patients with type 2 diabetes have shown that daily γ-oryzanol intake reduces systemic inflammatory markers such as C-reactive protein (CRP), interleukin-6 (IL-6), and interferon-gamma (IFN-γ), indicating its anti-inflammatory efficacy in metabolic contexts." (PMID 41009004, 2025). "Importantly, IL-1 antagonism reduces levels of CRP, IL-6 and leucocytosis in those with type 2 diabetes." (PMID 39496966, 2025). "However, other researchers found an increased trend of CRP and HbA1c in type 1 adults, which reflects data from individuals with type 2 diabetes and type 1 pediatric patients (HbA1c data only)." (PMID 40141192, 2025). "Furthermore, serum ANRIL levels were elevated in individuals with type 2 diabetes and strongly correlated with pro-inflammatory markers leptin and hs-CRP (both p < 0.001), in line with findings from studies on diabetic and cancer patients." (PMID 40940402, 2025). "To explore this hypothesis, we evaluated key clinical parameters, including age, gender, BMI, CRP, D-dimer levels, the presence of malignancy, the use of corticosteroid, and type 2 diabetes." (PMID 40620438, 2025). "This single-center quasi-experimental study demonstrated that 12 weeks of nightly melatonin supplementation (5 mg) significantly improved cognitive performance and reduced HbA1C and CRP levels in patients with type 2 diabetes and mild to moderate cognitive impairment." (PMID 41281014, 2025). "These elevations are accompanied by higher levels of NT-proBNP and CRP during morning exercise, suggesting that low-grade inflammation in the presence of high cortisol levels amplifies glycaemic excursions in individuals with type 2 diabetes." (PMID 40580209, 2025). "Inflammation markers like IL-6 and CRP are related to heart disease and type 2 diabetes." (PMID 39685657, 2024). "CRP levels in type 2 diabetes are often elevated, increasing the potential margin of reduction." (PMID 38999806, 2024). "A recent exploratory analysis of four different phase 3 trials from the clinical development programs of both subcutaneous and oral semaglutide, a glucagon like peptide-1 receptor agonist, showed that semaglutide reduced CRP compared to comparator drugs in individuals with type 2 diabetes." (PMID 38730445, 2024). "These researchers concluded “that targeting cytokines, cytokine receptors, and inflammation-associated nuclear transcription factors, such as IL-1β, IL-αR, TNF-α, and NF-kB alone or in combination, can significantly reduce the level of FPG, HbA1c, and CRP in patients with type-2 diabetes." (PMID 39199336, 2024). "The authors pointed to upstream inflammatory effectors as possible causal mediators as they observed a clear association between CRP and incident type 2 diabetes, but no indication of causality." (PMID 38730445, 2024).
type 2 diabetes (continued). "Furthermore, neither MR-Egger regression nor MR-PRESSO detected the presence of horizontal pleiotropy.We further investigated the colocalization of idiopathic pulmonary fibrosis, asthma, asthmatic pneumonia, Parkinson’s disease, and type 2 diabetes with CRP." (PMID 39229261, 2024). "and the cumulative incidence of type 2 diabetes stratified by plasma CRP < or ≥ 2 mg/L (d)." (PMID 38730445, 2024). "At age 60 years, the lowest and highest risk (no type 2 diabetes and a CRP < 2 mg/L and both type 2 diabetes and a CRP ≥ 2 mg/L) categories had cumulative incidences of 5.2% and 19.0% for IHD, respectively, equivalent to a 365% increase in risk of IHD." (PMID 38730445, 2024). "However, it should be reiterated that CRP and IL-6 levels generally tend to be low in both Japanese women and men, and the prevalence of Type 2 diabetes in the MIDJA participants was only 7%." (PMID 39765763, 2024). "The primary outcome measures—changes in type 2 diabetes (HbA1c), cardiovascular disease (CRP) and chronic kidney disease (ACR)—will be obtained by blood/urine spot from a finger prick/urine collection at baseline and 12-month follow-up via point-of-care testing." (PMID 36833652, 2023). "We are currently inconclusive on the association of drinking, coffee intake, composition of diet structure, sedentary, insomnia, sleep duration, serum lipid, C-reactive protein, fasting insulin, type 2 diabetes, thyroid dysfunction, testosterone and oestradiol with OSA." (PMID 38085646, 2023). "Besides, it is no efficient in controlling parameters other than hemodynamic system (HbA1c, endothelin 1 serum level, high sensitivity C-reactive protein plasma level and interleukin six serum level) in type II diabetes patients." (PMID 36814496, 2023). "We excluded 294 individuals with non-singleton births, positive GAD (GAD) antibody (>30 kU/l) (to avoid potential misclassification of type 2 diabetes with autoimmune diabetes) or high-sensitivity C-reactive protein (hsCRP) >30 mg/l (indicating acute illness at time of enrolment)." (PMID 37303007, 2023). "The main result of this study was that the rate of ABL had a higher AUROC value than hs-CRP, suggesting that individuals who have type 2 diabetes may be identified from the results of ROC analysis." (PMID 35805792, 2022). "In conclusion, low-grade inflammation, as measured by hs-CRP, is an independent risk factor for vascular- and all-cause mortality, in high-risk type 2 diabetes patients with and without manifest vascular disease." (PMID 34753497, 2021). "For instance, in a cross-sectional study of Type 2 diabetes, plasma leptin levels were associated with coronary artery calcification (CAC), a measure of coronary atherosclerosis, after adjusting for adiposity and C-reactive protein (CRP)." (PMID 34064112, 2021). "Furthermore, we found highly suggestive evidence between higher CRP and risk of CHD, type 2 diabetes and mortality or CVD on stable CAD patients and on unstable CHD/ACS/angina patients." (PMID 32978716, 2021). "The inflammatory response based on serum CRP levels correlated with patients suffering from type II diabetes, a higher cumulative joint score, an increased number of affected joints, positive DC sign on ultrasound, elevated serum uric acid, and elevated leukocyte count in the joint aspirate." (PMID 34063875, 2021). "However, there is a paucity of literature on the correlation of salivary CRP levels with HbA1C levels in type 2 diabetics." (PMID 33676486, 2021). "Low grade inflammation, as measured by hs-CRP, is an independent risk factor for vascular- and all-cause mortality but not for cardiovascular events in high-risk type 2 diabetes patients." (PMID 34753497, 2021). "The aim of the present study is to evaluate the relation between hs-CRP plasma levels and cardiovascular events and all-cause mortality in high-risk type 2 diabetes patients with and without clinical manifest vascular disease." (PMID 34753497, 2021).
type 2 diabetes (continued). "Further support for this hypothesis comes from the relationship observed between high CRP levels and type 2 diabetes in our study." (PMID 33114064, 2020). "8.3% of the subjects were with type 2 diabetes and 17.1% with high hs-CRP level." (PMID 32280714, 2020). "CRP levels have also been shown to raise when circadian rhythm is altered, in type-2 diabetes, and with dietary habits or fast/fed status, factors that might have contributed to the observed increase in CRP." (PMID 32718098, 2020). "IM patients with type 2 diabetes (main group) have a 2.7 times increase in CRP content, 4.4 and 3.1 times in proinflammatory IL-6 and TNF-α, respectively, as well as anti-inflammatory IL-10 concentration of 1.9 times higher relative to the indicators in the control group." (PMID 32341698, 2020). "This site has previously been associated with higher scores on tests of vocabulary and speed of information processing in an EWAS meta-analysis of cognitive abilities (LBC1936 contributed to this study), as well as with type 2 diabetes and BMI—both strong correlates of circulating CRP levels." (PMID 32718350, 2020). "Furthermore, exenatide and dulaglutide reduced the circulating levels of C-reactive protein (CRP) in patients with type 2 diabetes." (PMID 31295940, 2019). "Our aim was to identify whether low-grade inflammation, reflected by C-reactive protein (CRP), explains the higher risk for incident type 2 diabetes (T2D) among ethnic minorities." (PMID 31882814, 2019). "Moreover, CRP levels were higher in patients with prediabetes and type 2 diabetes than in controls in our study, suggesting a relationship between inflammation and NAFPD." (PMID 31664423, 2019). "Epidemiological studies have reported that levels of pro-inflammatory and inflammatory cytokines such as C-reactive protein (CRP), TNF-α, IL-1β, and IL-6 were elevated in patients with type 2 diabetes and were associated with the development of type 2 diabetes." (PMID 30857216, 2019). "Additionally, a randomized controlled clinical trial suggested that probiotics and prebiotics as functional food reduced inflammatory markers such as CRP in patients with type 2 diabetes." (PMID 29382113, 2018). "Higher CRP levels have been related to insulin resistance, suggesting that elevated inflammation may drive progression of type 2 diabetes." (PMID 30538987, 2018). "In general, these studies reported no significance between C-reactive protein and the risk of developing type 2 diabetes after adjusting for body mass index, waist–hip ratio in addition to body mass index and without adjusting for any patient characteristics." (PMID 29910771, 2018). "Furthermore, an association between PLTP activity and inflammatory marker CRP was found in patients with CVD and type 2 diabetes." (PMID 29565987, 2018). "In addition, the authors found that in the subgroup with type 2 diabetes, zonulin increased significantly together with high-sensitivity CRP." (PMID 29134616, 2018). "Indeed, elevated CRP and IL-6 independently predicted the development of type-2 diabetes across a 4-year period in the Women's Health Study, after controlling for BMI and family history of type-2 diabetes." (PMID 30538987, 2018). "Moreover, increased levels of inflammatory markers such as CRP and white cell blood count correlate with incident type 2 diabetes." (PMID 29082259, 2017). "Elevated levels of IL-6 and CRP have been shown to predict the development of type 2 diabetes." (PMID 28813433, 2017). "In fact, a rise in inflammatory markers such as C-reactive protein (CRP), haptoglobin, and fibrinogen in the blood is recognized in diabetic patients, and increases in interleukin- (IL-) 1β, IL-6, and CRP in the blood are predictive factors for type 2 diabetes." (PMID 28168013, 2017).
type 2 diabetes (continued). "In examinations concerning the concentrations of pro-inflammatory markers in patients suffering from type 2 diabetes, significantly higher concentrations of IL-6, CRP, and fibrinogen were demonstrated in the case of the co-occurrence of PAD than without this disease." (PMID 27834825, 2016). "In patients with type 2 diabetes, sitagliptin (100 mg/day) therapy significantly reduced the plasma levels of C-reactive protein (CRP), IL-6, IL-18, secreted phospholipase-A2, soluble intracellular adhesion molecule- (ICAM-) 1, and E-selectin compared with placebo." (PMID 27110066, 2016). "ICAM-1 and VICAM-1 have been reported to predict the development of type 2 diabetes in women irrespective of other known risk factors including abdominal obesity or CRP levels as a marker of inflammation." (PMID 26981539, 2016). "Moreover, A-FABP was found to be associated with several variables including HbA1C, BMI, TG, HDL-C, HOMA-IR, WHR, CRP, and IL-6 in obese subjects with type 2 diabetes." (PMID 27819006, 2016). "Recent studies revealed that low grade inflammation is reflected by increased levels of hsCRP in patients with type 2 diabetes and small increased CRP level predict the likelihood of developing cardiovascular events both in diabetic and nondiabetic populations." (PMID 27684378, 2016). "High levels of IL-6 and CRP predicted incident type 2 diabetes." (PMID 25722960, 2015). "The use of CRP as an indicator of the efficacy of statin therapy on CVD risk in patients with type 2 diabetes is not supported by these data." (PMID 25899452, 2015). "High levels of IL-6, TNF-α receptor 2 and CRP predicted incident type 2 diabetes." (PMID 25722960, 2015). "This is in agreement with the reports on decreased ApN levels in patients with prediabetes and type 2 diabetes and a negative association between plasma ApN and the levels of CRP and WBC." (PMID 26089882, 2015). "Our study population of patients with type 2 diabetes without prior CVD had intermediate CRP values and were at modest risk of CVD events." (PMID 25899452, 2015). "The use of CRP as an indicator of efficacy of statin therapy on CVD risk in patients with type 2 diabetes is not supported by these data." (PMID 25899452, 2015). "There are several possible mechanisms by which CRP may mediate the effect of cigarette smoking on the development of type 2 diabetes." (PMID 25105149, 2014). "CRP was measured in 1,037 patients (57% male) with newly diagnosed Type 2 DM included in the prospective nationwide Danish Centre for Strategic Research in Type 2 Diabetes (DD2) project." (PMID 25163828, 2014). "Studies have shown that CRP, IL-6, and other cytokines mediate insulin metabolic pathways, weaken insulin receptor signal transduction, induce disorders of glucose metabolism, and stimulate type 2 diabetes." (PMID 25132859, 2014). "The aim of this study was to determine the effect of NSPT as compared to thorough OHI on the metabolic control as well as systemic inflammatory marker, hs C-reactive protein (hs-CRP), among a population of type 2 diabetes afflicted with moderate to severe chronic periodontitis." (PMID 24965218, 2014). "Some studies concluded that IL-6 levels, but not CRP or fibrinogen levels, add significantly to the prediction of macrovascular events and mortality in individuals with type 2 diabetes who have baseline CVD or risk factors." (PMID 24955583, 2014). "Similarly, our study found that higher serum CRP levels were significantly related to type 2 diabetes, after adjusting for potential confounders." (PMID 25105149, 2014). "The observed relationship between the daily smoking quantity and type 2 diabetes may have been mediated by CRP." (PMID 25105149, 2014). "Given anti-inflammatory properties of the normal endothelium, this concept is also concordant with a joint synergistic contribution of higher hs-CRP and peripheral microvascular endothelial dysfunction, but not IR, to the risk of new-onset type 2 diabetes." (PMID 23578341, 2013).
type 2 diabetes (continued). "Further analysis of this putative atorvastatin-response subgroup showed characteristics of systemic subclinical inflammation as seen in type 2 diabetes, increased BMI, higher levels of fasting C-peptide and, besides CRP, higher systemic concentrations of IL-6, IL-1RA, sICAM-1 and E-selectin." (PMID 22448235, 2012). "In this study, a highly significant positive association was found between hs-CRP levels and incident type 2 diabetes, but this association was no longer significant after multivariate adjustment, a finding also reported previously." (PMID 23251619, 2012). "A positively correlation was found between serum HSP70 and asymmetric dimethylarginine (ADMA) with high hs-CRP levels in type 2 diabetes patients suggest that both ADMA and HSP70 have similarly an inhibitory function on nitric oxide synthase (NOS) in inflammatory and oxidative stress situation." (PMID 22834788, 2012). "Interestingly, an anti-inflammatory CRP-lowering activity of atorvastatin was observed in a study of type 2 diabetes patients only for the subgroup with increased levels of CRP (>2 mg/l)." (PMID 22448235, 2012). "So, GI or GL diets may be of importance in the development of type 2 diabetes, possibly due to its effect on CRP concentrations." (PMID 21804937, 2011). "In this study, we investigate the effect of argan oil consumption on serum lipids, apolipoproteins (AI and B), CRP, and LDL susceptibility to oxidation in type 2 diabetic patients which are known to have a high level of cardiovascular risk due to lipid abnormalities and lipid peroxidation." (PMID 22114593, 2011). "In this Dutch population, GL was associated positively with CRP at baseline, but not with risk of type 2 diabetes." (PMID 21804937, 2011). "In this study, adiponectin was inversely associated with CRP in overweight and obese women only, whereas the adiponectin-CRP association was independent of BMI in previous studies among apparently healthy postmenopausal women and women with type-2 diabetes." (PMID 21331287, 2011). "We have studied the associations of hs-CRP concentrations in coronary patients with and without type 2 diabetes." (PMID 23675214, 2011). "After adding CRP at baseline to model 3, RRs for risk of type 2 diabetes did not change considerably (RRGI T3 versus T1: 0.96 (95%CI 0.75, 1.22); RRGL T3 versus T1: 0.99 (95%CI 0.73, 1.35))." (PMID 21804937, 2011). "Our observation among Peruvians raise the possibility that inflammatory markers, like CRP, might provide an adjunctive method for early detection of type 2 diabetes although further investigation is needed to confirm this observation." (PMID 20482756, 2010). "CRP and MCP-1 were associated with abnormal glucose regulation independently of each other, indicating that these markers probably are involved in different pathological processes associated with type 2-diabetes." (PMID 20809989, 2010). "The aim of this study therefore was to determine whether CRP was mediating the association between HNF1A G319S and type 2 diabetes in an Aboriginal Canadian community known to have a high prevalence of type 2 diabetes." (PMID 20716378, 2010). "Furthermore, adiponectin is inversely related to various inflammatory markers such as tumour necrosis factor-α (TNF-α), C-reactive protein (CRP) and interleukin-6 (IL-6) in normal subjects and patients with type 2 diabetes and CVD." (PMID 20066136, 2008). "In conclusion, studying more than 11,000 individuals newly diagnosed with type 2 diabetes, we found that elevated YKL-40 levels were strongly associated with increased risk of liver cancer, and to a lesser extent, bladder cancer, clearly outperforming CRP for these cancers." (PMID 40188292, 2025). "However, serum CRP has been shown to exhibit profound intra- and inter-individual variability and the mechanistic underpinnings of elevated CRP in patients with type 2 diabetes remain uncertain." (PMID 38725572, 2024).